SMAD3 (SMAD family member 3)
Diseases named in the same sentence as SMAD3 in open-access papers (continued):
Sharing a sentence is not in itself a finding about the gene and the disease.
cancer (continued). "This study indicate that targeting SMAD3 may be an effective therapy to protect against cancer progression and increase OS." (PMID 32140069, 2020). "The responses associated with TGF-β-induced S423/S425 Smad3 phosphorylation are clearly different in cancer/embryonic and mature non-malignant human cells." (PMID 33295886, 2020). "Studies in cancer cells have demonstrated direct interaction of Akt and Smad3 to sequester Smad3 outside of the nucleus, although it remains to be determined whether the same mechanism exists in skeletal muscle." (PMID 32858949, 2020). "c-Myc directly associates with the MH2 domain of SMAD2 and SMAD3 to inhibit the TGF-β-induced transcriptional activity of Sp1 and SMAD/Sp1-dependent transcriptions of the p15Ink4B gene and eventually promotes cell growth and cancer progression." (PMID 32340410, 2020). "The relationship between SMAD3 and cancer patients' prognosis has been reported." (PMID 32140069, 2020). "We analyzed the methylation level of cg24032190 in SMAD3 in different cancer types." (PMID 33036415, 2020). "Therefore, the TGF‐β1/Smad3 pathway can not only inhibit hepatocyte growth but also promote the development of liver fibrosis and cancer, meaning that it inhibits tumour cell proliferation and also promotes mitosis." (PMID 32406200, 2020). "In conclusion, SMAD3 methylation levels vary in colorectal tissue based on the type of cancer." (PMID 33036415, 2020). "SMAD3 promotes cancer progression through the TGF-β signaling pathway." (PMID 33036415, 2020). "Collectively, these data provide a strong indication that SMAD3 expression may be repressed by cancer-induced reprogramming, resulting in SMAD3 promoter hypermethylation in gastric CAMs." (PMID 30624614, 2019). "Screening of several TNBC cell lines showed altered Smad2 and Smad3 protein levels compared to normal mammary epithelial cells, suggesting the possibility that it could play an important role in the escape of cancer cells from TGF-β mediated growth inhibition." (PMID 31798766, 2019). "However, SMAD3 is also likely to play a role as a cancer suppressor in NSCLC through other mechanisms." (PMID 30594196, 2018). "The versatile SMAD3 candidate has been shown to influence the immunosurveillance of cancer." (PMID 30102725, 2018). "FHL1 acts in activation of the tumor suppressor gene p21 and repression of the oncogene c-myc through physically and functionally interacting with Smad2, Smad3 and Smad4 that are important regulators of cancer development and progression in a casein kinase 1δ-dependent manner." (PMID 30379883, 2018). "The CEP131 gene is involved in cell proliferation and migration through the activation of the phosphoinositide 3-kinase (PI3K/Akt) signaling and the SMAD3 gene is a key mediator of the transforming growth factor-β (TGF-β) signaling pathway involved in cancer progression." (PMID 30102725, 2018). "The role of Smad3 in many cancers is an emerging area of intense research." (PMID 30594196, 2018). "Furthermore, systemic treatment with a Smad3 inhibitor SIS3 effectively suppresses cancer progression." (PMID 28262747, 2017). "Thus TGF-β/Smad3 signalling facilitates cancer progression by suppressing NK cell production via downregulating E4BP4." (PMID 28262747, 2017). "These novel findings suggest that TGF-β may act via a Smad3-dependent mechanism to facilitate cancer progression by suppressing NK cell production." (PMID 28262747, 2017). "We next investigated the underlying mechanisms whereby mice lacking Smad3 were protected against cancer growth and metastasis." (PMID 28262747, 2017). "Our study demonstrated that Smad3-mediated inhibition of E4BP4 transcription may be a critical mechanism by which deletion of Smad3 promotes NK cell immunity and suppresses cancer progression." (PMID 28262747, 2017). "Taken together, our results revealed that targeting Smad3-dependent microenvironment may represent a novel and effective therapy for invasive cancer." (PMID 28262747, 2017).
cancer (continued). "As Smad3−/− microenvironment was able to protect mice against cancer progression by dramatically increasing NK cell production, we further investigate the unexplored role of Smad3 as a negative regulator in the NK cell development." (PMID 28262747, 2017). "SMAD3 inhibition rescues cancer cell proliferation in PC3 cells." (PMID 26924343, 2016). "The role of SMAD3 in the regulation of genes important for cell fate, such as differentiation, growth and death, implies that an alteration in its activity or repressing of its activity can lead to the formation or development of cancer." (PMID 27601936, 2016). "Interestingly, the TGFβ-Smad3 signalling pathway has previously been shown to promote cancer cell survival and metastasis." (PMID 27566553, 2016). "According to these studies, Smad2 linker phosphorylation (on residues 245, 250 and 255) correlates with fibrotic EMT, while Smad2 (on residue 220) and Smad3 (on residue 179) linker phosphorylation correlate with the invasive behavior of fibrotic liver cells that progress to carcinoma development." (PMID 27367735, 2016). "Smad3, on one hand, has been firmly linked to the process of EMT, and knocking out Smad3 in various epithelial cell types, including keratinocytes in the mouse skin, it protects these animals from chemically-induced aggressive carcinoma development." (PMID 27367735, 2016). "While, depletion of Smad3 reduced KLF17 expression in different cancer cells." (PMID 25766320, 2015). "Interestingly, KLF17 expression was strongly correlated with Smad3 level in all tested cancer samples except 1 (labeled as KLF17+ and Smad3+)." (PMID 25766320, 2015). "Therefore, our study suggests that Smad3 linker region can be an important target of LTB4 inflammatory signal leading to cancer cell proliferation." (PMID 26497676, 2015). "It has been shown that inhibitors that decrease levels of Smad2 and Smad3 through interruption of TGF-β signaling could be valuable tools for treatment of human cancers such as CRC, glioblastoma and breast cancer." (PMID 25980495, 2015). "However, phospho-Smad3 levels were reduced in malignant tumors and even further diminished in the metastatic tissue samples." (PMID 25885043, 2015). "KLF17 shows positive correlation with Smad3 levels in cancer samples." (PMID 25766320, 2015). "It has been reported that TGF-β induces autophagy in cancer cells through Smad2/Smad3 signaling pathway, and autophagy is an essential metabolizing process for CSC origin and maintenance, we reasoned that hsa-miR-140-5p may impact the colorectal CSC survival." (PMID 25980495, 2015). "However, further investigations on how POGLUT1 interacts with these proteins and how POGLUT1 affects Smad3 phosphorylation levels are required in order to understand the specific mechanism of POGLUT1 in cancer." (PMID 25009645, 2014). "Conversely, in case of low or absent Rac1b expression/ activity or a low ratio of Rac1b:Rac1 expression as in Panc-1 cells, cancer cells might experience an enhanced potential for Smad3-dependent or independent migration, invasion, and possibly metastasis." (PMID 24378395, 2014). "Previous studies have demonstrated that the decreased expression levels of TβRI, SMAD3 and SMAD4 may cause cancer cells to escape the growth inhibition of TGF-β1, and the increased expression of SMAD7 may block the inhibitory effects of TGF-β1." (PMID 25295107, 2014). "Last, the repair and immune abnormalities, in concert with elevated oncogene expression (c-myc) in Smad3−/− epithelial cells, may favor increased progression to cancer as compared to Smad3+/− and WT animals." (PMID 24244446, 2013). "Indeed, while increased Smad3 linker phosphorylation has been described in cancer, this study is the first report of increased Smad3 linker region phosphorylation in kidney fibrosis." (PMID 24391884, 2013). "SiRNA-mediated silencing of SMAD3 increases TGF-β-induced cancer cell migration." (PMID 24260584, 2013).
cancer (continued). "It remains to be determined whether epidermal specific Smad3 deletion will have similar or distinct effects on cancer development as the Smad2 epidermal null." (PMID 23326666, 2012). "In cancer, it is controversial whether disruption of the Smad3 gene contributes towards tumorigenesis." (PMID 22539990, 2012). "However, relatively few studies on the roles of Smad2 and Smad3 in TGF-β signalling have been performed in human epithelial cells from which most cancers arise." (PMID 21624123, 2011). "Thus, STAT3 and Smad3 sequential activities in the cancer cells depended on IL-6 and TGF-β secreted in the supernatant and required NF-κB activity." (PMID 20520770, 2010). "Furthermore, Smad3 knockout animals survive after birth, but die before old age due to chronic infections, accelerated rate of cancers and T-cell dysfunction." (PMID 19732043, 2009). "Notably, MYC, SMAD3, and TGFB1 were implicated in more than four cancer hallmarks." (PMID 40149461, 2025). "Thus, by increasing the production of IFN-γ and GM-CSF, Smad3-silenced NK cell therapy may promote the polarization of APC-like neutrophils with enhanced anti-cancer effects and immunostimulatory functions." (PMID 38878186, 2024). "Furthermore, the role of SMAD3 in DMD shares mechanistic similarities with its function in cancer metastasis, where it regulates cellular proliferation, migration, and invasion—processes similarly detrimental in DMD albeit through different pathological outcomes." (PMID 39415830, 2024). "In addition, crosstalk exists between STAT3 signaling and Snail-Smad3/TGF-β1 in cancers." (PMID 38136312, 2023). "Therefore, SMAD3 and MMT may be a new therapeutic target for cancer-associated fibroblasts for cancer immunotherapy." (PMID 37685308, 2023). "Thus, our work suggests that Smad3 signaling in neutrophils may represent a therapeutic target for cancer immunotherapy." (PMID 37002229, 2023). "Thus, the study suggests that SMAD3 signalling in neutrophils may be a therapeutic target for cancer immunotherapy." (PMID 37685308, 2023). "Hence, Smad3 promotes cancer by influencing reshaping of TME." (PMID 36765396, 2023). "The effects of SMAD3 and Notch1 are almost the same in cancer cell migration, as knockdown of either of the two could decrease the migration advantage seen in the overexpression of NUMB-p66, and overexpression could rescue the migration reduction seen in p65/p66 knockdown." (PMID 35457181, 2022). "Moreover, pharmacological inhibition of SMAD3 methylation dramatically inhibited cancer metastasis." (PMID 35085106, 2022). "Also, there are many studies related to the role of SMAD3 in various cancers." (PMID 35291909, 2022). "Importantly, circMET regulated the expression of CDKN2A, a critical tumor suppressor gene, and SMAD3 which could maintain the stem cell properties of cancer stem-like cells." (PMID 35042525, 2022). "Thus, MMT may represent a novel therapeutic target for cancer, which can be precisely blocked by targeting Smad3 in the macrophages." (PMID 34791825, 2022). "However, some reports have indicated that Smad3 acetylation also activates EMT in several cancers." (PMID 34122724, 2021). "Besides targeting Smad3, overexpression of Smad7 also effectively inhibit cancer in animal models." (PMID 34514726, 2021). "Furthermore, SMAD3 is a negative prognostic factor of highly differentiated cancer, and association with male and female gender." (PMID 34138687, 2021). "However, the role of SMAD3 methylation in cancer is still unclear." (PMID 33036415, 2020). "However, knockdown SMAD3 had minimal effect on either ROS level or cancer stemness formation." (PMID 27903972, 2017). "Thus systemic Smad3-targeted therapy may represent a novel and effective therapeutic strategy for invasive cancer." (PMID 28262747, 2017). "Moreover, in this report, we investigated a previously unknown regulatory mechanism for the regulation of KLF17 by TGF-β/Smad3 signaling in cancer cells." (PMID 25766320, 2015).
cancer (continued). "Thus, induction of KLF17 by TGF-β/Smad3 may be one of the mechanisms to fight against cancer development." (PMID 25766320, 2015). "Finally, our study indicates that targeting KLF17 for cancer therapy may be beneficial for some human tumors having abnormal Smad3 proteins." (PMID 25766320, 2015). "However, we predict R-Smad-TMEPAI- Akt mediated proliferation of cancer cells may depend more on the suppression of p27 than of p21, since Smad3 is a cofactor for p21 transcription and Smad3 knockdown would inhibit p21 induction." (PMID 25352949, 2014). "There is evidence that SMAD3, as it lowers fibrosis, may also lower cancer." (PMID 25236373, 2014). "Furthermore, they provide evidence that Smad3/TGFβ is controlled by KRAS in both cancers." (PMID 24878567, 2014). "Furthermore, while Smad2 mutations in cancer have been described, no mutations in Smad3 or p21 have yet been reported." (PMID 22995475, 2012). "Since strategies for therapeutic targeting of the TGF-β signalling pathway are being pursued, revealing the identity of factors that modulate the relative activation of Smad2 or Smad3 in the TGF-β response may provide target(s) for more effective strategies for cancer therapy." (PMID 21624123, 2011). "Furthermore, in rat prostatic epithelial cells, Smad2 was shown to be critical for the proapoptotic effect of TGFβ in a premalignant basal cell line (NRP152), while Smad3 mediated the apoptotic response in a malignant luminal carcinoma cell line (NRP154) derived from the same rat prostate." (PMID 20942910, 2010). "CD11c impaired cancer cell antigen presentation and fostered EMT through up-regulation of mothers against decapentaplegic homolog 3 (SMAD3) phosphorylation in human ESCC cell lines." (PMID 41799568, 2026). "Specifically, it interacts with a transcriptional complex composed of DDX17, SMAD3, and TGIF2, which drives the expression of SOX2, a key regulator of cancer stem cell properties." (PMID 41294868, 2025). "By disrupting harmful processes driven by SMAD3 and NOTCH signaling, calycosin can reduce cancer progression." (PMID 40361382, 2025). "As a member of the SMAD proteins family, SMAD3 acts as a mediator of the TGF-superfamily to regulate signaling, regulating cell proliferation, apoptosis, immune monitoring, and cancer metastasis." (PMID 40164592, 2025). "Crosstalk between SMAD3 and STAT3 has been demonstrated in numerous conditions, especially in cancer." (PMID 38902234, 2024). "The crosstalk between the JAK/STAT pathway and other pathways, such as the formation of complexes between STAT3/SMAD3 and STAT3/CD44, contributes to the generation of cancer stem cells." (PMID 38553760, 2024). "The GSE20549 dataset reveals a positive correlation between SMAD3 and integrin subunit alpha 6 (ITGA6), a transmembrane glycoprotein adhesion receptor protein widely expressed in various tumors, known to facilitate cancer cell migration and invasion." (PMID 38493128, 2024). "Paclitaxel (PTX), as a diterpenoid alkaloid exhibiting anti-cancer properties, it has the ability to reverse AEC’s EMT, enhance miR-140 expression, suppress Smad3 and p-Smad3, and elevate E-cadherin levels." (PMID 39479511, 2024). "There was a greater difference in the expression of SMAD2, SMAD3, SMAD4, SMAD5, and SMAD9 between cancer and normal samples." (PMID 38514720, 2024). "TWIST1 is extensively expressed in cancer, and through controlling the TGF-β/SMAD3 signaling pathway, it promotes EMT and carcinogenesis." (PMID 38589525, 2024). "We have identified C1orf106 as a novel SMAD3-dependent TGF-β target gene in a variety of immortalised and cancer cell types." (PMID 39329715, 2024). "Analysis of the function of SMAD3 using GSEA showed that high SMAD3 expression was related to multiple types of cancer including NSCLC, and cancer-related pathways such as PI3K/Akt/mTOR and KRAS." (PMID 38493128, 2024).
cancer (continued). "The investigators also recognized macrophage-specific SMAD3 as a key modulator of MNT promotion, which represents a precision therapeutic target for cancer-related pain." (PMID 38022518, 2023). "Lactobacillus cocktail and C. butyricum promote cancer cell apoptosis and suppress cancer cell proliferation and EMT by inhibiting Wnt/β‐catenin pathway, NF‐κB pathway, and Smad3 pathway." (PMID 37937304, 2023). "Distinct signaling pathways are involved in EMT mediated by TGF-β, among which SMAD3 is a key mediator of EMT and usually overexpressed in numerous cancers." (PMID 35457181, 2022). "Incubation of MCF7 cells with TβRII+ EVs up-regulated TGF-β-SMAD3/4 target genes to a level similar as with TGF-β treatment, including key transcriptional inducers of EMT and markers of cancer stemness." (PMID 35915084, 2022). "Macrophage‐specific silencing of Smad3 effectively blocks MMT, thereby inhibiting CAF‐mediated cancer progression." (PMID 34791825, 2022). "To compare the impact of the modulation of SMAD2 or SMAD3 expression on the invasive properties of cancer cells, we used HT-1080 and MDA-MB-231 cells overexpressing shRNA directed against SMAD2 or SMAD3." (PMID 35681731, 2022). "Our study revealed several cancer driver genes that differed between the high and low m5C score groups, including KRAS, FBXW7, and SMAD3." (PMID 35433474, 2022). "More importantly, macrophage‐specific deletion and pharmaceutical inhibition of Smad3 effectively block MMT, therefore, suppressing the CAF formation and cancer progression in vivo." (PMID 34791825, 2022). "Thus, Smad3 may represent a druggable target for targeting MNT-driven neurogenesis in cancer." (PMID 36206343, 2022). "A functional synergism was also observed between Notch1 and SMAD3 in the regulation of EMT and cancer cell migration." (PMID 35457181, 2022). "More importantly, we demonstrated that macrophage‐specific silencing and pharmacological inhibition of Smad3 effectively blocked MMT, therefore, largely suppressing CAF formation and cancer progression in vivo." (PMID 34791825, 2022). "The major drivers of cardiac muscle wasting in cancer patients are autophagy activation by the cytokine-NFkB, TGF β-SMAD3, and angiotensin II-SOCE-STIM-Ca2+ pathways." (PMID 35326441, 2022). "Galectin-9 expression in these cells was upregulated by TGF-β, as in other cancer cells studied in the past, and this correlated with TGF-β-induced Smad3 phosphorylation." (PMID 35223897, 2022). "Our data further reveal that NUMB p65/p66 isoforms increase Notch1 activity, and N1ICD works in concert with SMAD3 to promote EMT and thus enhance cancer cell migratory abilities." (PMID 35457181, 2022). "Regarding the mechanism of this cancer-like vascular remodeling, TGF-β/Smad3, BMPR2 pathways, and O2-sensitive voltage-gated K + channels are believed to be the important pathways." (PMID 35002707, 2021). "SMAD3, as a critical mediator of TGF-β signaling pathway, has been reported as a promoter of EMT and migration in multiple cancer types." (PMID 33758603, 2021). "Some of the related pathways are usually altered in some types of cancer as Beta-catenin independent WNT-signaling, SMAD2/SMAD3, tight junction, ABC transporters, etc.24–27." (PMID 33649335, 2021). "SMAD family member 3 (SMAD3) is an attractive candidate for a predictive and prognostic marker in cancer." (PMID 35002714, 2021). "SMAD3 is a potential biomarker in PDAC, which promotes cancer's malignant potential through EMT induction in malignant cells." (PMID 33521362, 2021). "Encouragingly, in this study, we also detected that AANG markedly suppressed our reported Smad3‐mediated NK immunity suppression in the R‐HepG2 xenografts in vivo, thereby blocking the TME‐driven cancer development and progression in mice." (PMID 34514726, 2021). "In vitro cell experiments were used to further explore the effects of SMAD3 on proliferation, apoptosis, and migration of AGS and MGC803 cancer cells." (PMID 34138687, 2021).